TLR4 (toll like receptor 4)
Diseases named in the same sentence as TLR4 in open-access papers (continued):
Sharing a sentence is not in itself a finding about the gene and the disease.
Cognitive impairment (continued). "H2S reduced the cognitive impairment of rats after SAH by ameliorating neuroinflammation in microglia, potentially via the TLR4/NF-κB pathway." (PMID 32754015, 2020). "As expected, the specific TLR-4 inhibitor VIPER remarkably attenuated the LPS-induced neuroinflammation; moreover, VIPER abolished the cognitive impairment following neuroinflammation." (PMID 30962497, 2019). "Pharmacological or genetic inhibition of TLR4/NF-κB signaling can reduce microglial activation and neuronal apoptosis, but its contribution to sevoflurane-induced cognitive deficits has not been determined." (PMID 41281895, 2025). "Apart from TLR4, LPS increases the expression of the receptor for Advanced Glycation End-products (RAGE), which is critically involved in the pathology of AD, including Aβ deposition, and cognitive impairment." (PMID 41516244, 2025). "Indeed, VIPER (viral inhibitory peptide for TLR4), which is a TLR-4-specific inhibitory peptide, inhibited LPS-induced neuroinflammation and cognitive impairment." (PMID 36552802, 2022). "Quercetin could downregulate inflammatory response through TLR4/ NF-κB pathway, thereby attenuating HINS-induced anxiety, hippocampal memory impairment, and cognitive impairment in later life following HINS." (PMID 35223693, 2022). "This study investigated the hypothesis that H2S can reduce cognitive impairment after SAH, potentially by ameliorating neuroinflammation mediated by the TLR4/NF-κB pathway in the brain." (PMID 32754015, 2020). "LPS entering the brain then bind to Toll-like receptor 4 (TLR4) receptors on microglia, initiating the downstream NF-κB signaling pathway via MyD88, leading to the secretion of large amounts of pro-inflammatory cytokines, resulting in more intense neuroinflammation and cognitive impairment." (PMID 39101143, 2024). "Although TLR2 is shown to play a role in cognition, it would be incorrect to assume that it is the only pathway that might be involved in cognitive deficits in schizophrenia; other pathways or other TLRs such as TLR3 and TLR4 are involved with cognitive performance as well." (PMID 37627253, 2023). "A recent report showed that periodic administration of high doses of tannic acid (not condensed) prevents cognitive impairment in an AD-like model induced by lipopolysaccharide intraperitoneal injections (the major activator of the proinflammatory TLR4 signaling pathway)." (PMID 36290649, 2022). "TLR-4 activation induced by LPS triggers the expression of proinflammatory mediators, such as cyclooxygenase-2 (COX-2), nitric oxide synthase (iNOS), and proinflammatory cytokines, which are considered harmful mediators in neurodegeneration and cognitive deficits." (PMID 36670940, 2022). "Higher TLR4 levels may contribute to cognitive impairment by affecting white matter microstructure rather than subcortical volumes or cortical thickness in schizophrenia." (PMID 36051545, 2022). "Moreover, TLR4 activation modulates NMDAR subunits through HMGB1 signaling, suggesting that neuroinflammation may be critical in mediating the cognitive deficits." (PMID 27822212, 2016).
gastric cancer (134 papers, 2008 to 2026). A primary or metastatic malignant neoplasm involving the stomach. "For example, activation of TLR4 has been associated with increased proliferation of gastric cancer cells, particularly in the context of H. pylori infection." (PMID 39451226, 2024). "Researchers have shown that TAK‐242 selectively binds to TLR4, disrupts the interaction between LPS and TLR4, and inhibits downstream signaling pathways, which is effective in treating H. pylori‐associated gastric cancer." (PMID 38685971, 2024). "TLR4, activated in gastric cancer cells, is associated with resistance to chemotherapy, including common drugs used to treat this cancer, such as cisplatin and 5-fluorouracil (5-FU)." (PMID 39451226, 2024). "Overexpression of TLR4 in gastric cancer is also associated with more aggressive tumor characteristics, including the ability to invade and metastasize." (PMID 39451226, 2024). "For instance, TLR4 polymorphisms have been linked to an increased risk of developing some types of cancer, including colorectal and gastric cancer." (PMID 37998389, 2023). "The outcomes of our systemic review proved that the TLR4 polymorphism rs4986790 is associated with cancer, especially with gastric cancer, and this strong correlation are evident in Caucasians and Asian." (PMID 36281200, 2022). "TLR2 is involved in the pathogenesis of gastric cancer, and high levels of TLR4 are also associated with a higher risk of this tumor type." (PMID 34686626, 2021). "So far, several studies have found that TLR4 polymorphisms influence cancer susceptibility, such as gastric cancer, myeloma and hepatocellular carcinoma." (PMID 33585082, 2021). "Several studies found that TLR4 rs11536889 CC genotype or C allele was correlated with an increased risk of coronary artery disease, gastric cancer, and hepatitis A virus infection." (PMID 33426065, 2020). "As the most classical TLR in gastric cancer caused by helicobacter pylori, TLR4 has great value in immunotherapy of gastric cancer." (PMID 33469538, 2020). "This group detected an increased gastric cancer risk in TLR4 + 896A/G and TLR4 + 1196C/T polymorphism in a Caucasian population." (PMID 30837987, 2019). "In summary, the LPS/TLR4 pathway is linked to gastric cancer development, and the interaction between TLR4, MD-2 and CXCR7 is closely related to tumor growth and metastasis." (PMID 30636642, 2019). "The TLR4 polymorphisms are proposed to associate with various diseases such as gastric cancer, prostate cancer, primary open-angle glaucoma and bacterial infection." (PMID 30765614, 2019). "In short, we concluded that two polymorphisms (rs334348, rs10512263) in TGFBR1 were associated with risk of gastric cancer, and that TLR4 rs1927911 and TGFBR1 rs10512263 were associated with clinical outcomes of gastric cancer patients." (PMID 30479570, 2018). "Confirming the potential role of TLR4 in the progression of gastric lesions, some studies associated TLR4 polymorphisms with the risk of gastric cancer." (PMID 29670922, 2018). "Here, we conducted a case–control study to assess the susceptibility of polymorphisms in IL-16, TGFBR1 and TLR4 to risk of gastric cancer in a Chinese population, and the prognostic value of the polymorphisms was also evaluated by a retrospective study." (PMID 30479570, 2018). "In the case of H. pylori infection, TLR polymorphisms have been specifically implicated to enhance the susceptibility for infection (TLR1) and also the risk of developing H. pylori-induced gastric cancer (TLR4)." (PMID 25945326, 2015). "In the setting of H. pylori infection, gene expression of TLR2 and TLR4 is elevated in H. pylori-positive gastric patients, and TLR2 and TLR4 gene polymorphisms are associated with an increased risk of gastric cancer." (PMID 26064948, 2015). "TLR4 +896 and +1196 mutant polymorphisms have both been associated with gastric cancer risk in a meta-analysis." (PMID 26161647, 2015).
gastric cancer (continued). "To assess if the observed effect of TLR4 +896 and +1196 polymorphisms on G17 levels affect the incidence of peptic ulcer and gastric cancer, we compared the genotype distributions between the subject groups." (PMID 26161647, 2015). "A comprehensive search was conducted to identify all eligible case-control publications investigating the association between TLR4 polymorphisms and gastric cancer risk." (PMID 25290654, 2014). "As far as we know, this was the most comprehensive and updated meta-analysis investigating the association between TLR4 polymorphisms and gastric cancer risk." (PMID 25290654, 2014). "For TLR4 +896A/G polymorphism, individuals carrying the variant AG genotype had a significantly increased gastric cancer risk compared with the AA genotype (heterozygous model) (AG vs. AA: OR = 1.67, 95%CI = 1.39–2.01, P = 0.000)." (PMID 25290654, 2014). "Although the important role of TLR4 polymorphisms in the development of gastric cancer has been reported in recent years, the results are inconsistent." (PMID 25290654, 2014). "There were two studies investigating the association between TLR4 +896A/G polymorphism and H. Pylori infection in gastric cancer patients, and one study for TLR4 +1196C/T polymorphism." (PMID 25290654, 2014). "The results of Q-test in all genetic models for TLR4 +896A/G and +1196C/T polymorphisms in gastric cancer." (PMID 25290654, 2014). "To clarify and quantify the authentic effect of TLR4 (+896A/G and +1196C/T) polymorphisms on susceptibility to gastric cancer, we performed a meta-analysis including all eligible case-control studies." (PMID 25290654, 2014). "Growing studies explored the association of polymorphisms in TLR4 with susceptibility to gastric cancer, but the results have remained controversial and conflicting." (PMID 25290654, 2014). "To investigate the effect of two selected TLR4 (+896A/G and +1196C/T) polymorphisms on gastric cancer, we performed a meta-analysis." (PMID 25290654, 2014). "TLR4 Asp299Gly polymorphism has been shown to be associated with inflammatory diseases like Crohn's disease and gastric cancer and gastric lymphoma in different cohorts." (PMID 23936790, 2013). "In conclusion, this meta-analysis provided statistical evidence that the TLR2 and TLR4 polymorphisms were associated with cancer risk, particularly for gastric cancer." (PMID 24376595, 2013). "Our results are in contrast with those previously reported in several Caucasian populations that identified that TLR4+896G and TLR4+1196T alleles increased the risk of gastric carcinoma." (PMID 23776537, 2013). "There is growing evidence that TLR4 genetic polymorphisms impact on risk of cancer including gastric cancer and prostate cancer." (PMID 21559380, 2011). "An earlier report revealed that TLR4 was expressed on many tumor cell surfaces and associated with the risk of prostate cancer, nasopharyngeal carcinoma and gastric carcinoma." (PMID 22195048, 2011). "We found, for the first time, that rs10759932 variant genotypes (TC/CC) of the TLR4 gene were associated with a significantly reduced risk of gastric cancer in this high-risk population." (PMID 23554619, 2010). "In this study, we identified two SNPs located in the 5′ flanking region of TLR4 and found that rs10759932 variant genotypes (TC/CC) were associated with a significantly reduced risk of gastric cancer." (PMID 23554619, 2010). "Two non-synonymous polymorphisms of TLR4, Asp299Gly (rs4986790) and Thr399Ile (rs4986791), have been shown to be extensively involved in H. pylori infection-related disease, including gastric cancer." (PMID 23554619, 2010). "In this case-control study of gastric cancer, we investigated the associations of two SNPs in the 5′-flanking region of TLR4 with the risk of gastric cancer in a Chinese population." (PMID 23554619, 2010). "In general, the presence of some polymorphisms of the TLR4 gene might be associated with a higher risk of gastric cancer." (PMID 40362298, 2025).
gastric cancer (continued). "Various TLR4 SNPs have been associated with breast, prostate, colorectal, liver, lung, ovarian, cervical, nasopharyngeal, head and neck, and gastric cancer." (PMID 39684439, 2024). "In addition, in GC, Helicobacter pylori infection significantly induces miR‐18a‐3p and miR‐4286 expression through TLR4/NF‐κB, which is associated with the progression of gastric cancer." (PMID 38685971, 2024). "At the same time, analysis of ferroptosis-related genes associated normal tissue and gastric cancer tissues screened out 19 FerDEGs: ten of them, i.e., TLR4, KRAS, HSF1, was highly expressed and nine of them, i.e., MUC1, PROM2, MT1G, were lowly expressed in tumor tissues." (PMID 36936437, 2023). "TLR4 polymorphisms rs4986790 and rs4986791 may be associated with a significantly increased gastric cancer risk." (PMID 37370894, 2023). "The overall results from a meta-analysis of gastric cancer risk suggest that TLR4 polymorphisms (+896A/G and +1196C/T) may be associated with a significantly increased risk of gastric cancer in Caucasians." (PMID 37370894, 2023). "Chronic inflammation caused by bacterial infection is known to induce cancers as exemplified by Helicobacter pylori, which is associated with the development of gastric cancer via the activation of the TLR4 pathway by bacterial lipopolysaccharide followed by cancer growth through CagA-MET signaling." (PMID 34436224, 2021). "However, researchers didn’t find the correlation between TLR4 rs1927914 and the risk of lung or gastric cancer." (PMID 33585082, 2021). "TLR4 represents the most widely studied TLR in gastric cancer, and its polymorphism may associate with an increased risk of gastric cancer." (PMID 31467388, 2019). "Furthermore, TLR4 signalling activation in gastric cancer cells by lipopolysaccharides increase the risk of metastasis." (PMID 31467388, 2019). "High levels of TLR4 were also associated with a higher risk of gastric cancer." (PMID 30863783, 2019). "Thus, a study performed on Chinese population suggested an association between TLR4 3725 G/C polymorphism and an increased risk of developing gastric cancer." (PMID 30863783, 2019). "This is a study firstly discussed the relation of polymorphisms in genes of IL-16, TGFBR1 and TLR4 pathways and survival time of gastric cancer patients in Chinese population and our study could provide epidemiology data for further study." (PMID 30479570, 2018). "Similarly, polymorphisms in TLR4 has been implicated as risk factors for gastric cancer; however, the conclusion of susceptibility of these polymorphisms to gastric cancer risk remains elusive." (PMID 30479570, 2018). "The Sp1 binding site was generally hypomethylated in 15 gastric cancer tissues (38%) compared to normal tissues (80%) and in gastric cancer cell lines, and these results were associated with a high level of TLR4 mRNA expression." (PMID 26675260, 2016). "In conclusion, this meta-analysis demonstrates that TLR4 +896A/G and +1196C/T polymorphisms probably increase the susceptibility to gastric cancer mainly in Caucasians, while the susceptibility to gastric cancer in Chinese and other Asian population need to be proved in future large scale studies." (PMID 25290654, 2014). "The overall results suggest that TLR4 polymorphisms (+896A/G and +1196C/T) may be associated with a significantly increased gastric cancer risk in Caucasian." (PMID 25290654, 2014). "Many SNPs in TLR4 have been detected and studied, but two of the most typical SNPs in the fourth exon of coding sequence, +896A/G (ID: rs4986790) and +1196C/T (ID: rs4986791), were explored and reported extensively for the gastric cancer susceptibility." (PMID 25290654, 2014). "Notably, there is an opposite conclusion for the TLR4 Asp299Gly/Thr399Ile polymorphism that is associated with gastric cancer." (PMID 24959291, 2014).
gastric cancer (continued). "Consequently, we performed a comprehensive meta-analysis on the correlation between the TLR4 polymorphisms (+896A/G and +1196C/T) and gastric cancer risk." (PMID 25290654, 2014). "The distribution of the TLR4 +896A/G and +1196C/T polymorphisms in gastric cancer." (PMID 25290654, 2014). "To date, several studies focused on the association of TLR4 (+896A/G and +1196C/T) polymorphisms with precancerous lesions, gastric cancer, across different ethnicities, however, due to the limitations of subjects, the results were inconsistent and controversial." (PMID 25290654, 2014). "The TLR4 polymorphism (TLR4 Asp299Gly) decreases responsiveness to LPS and has a positive correlation with susceptibility to several infectious diseases including H. pylori-induced gastric cancer." (PMID 21647408, 2011). "The aim of this study was to evaluate whether polymorphisms in the toll-like receptor 4 (TLR4) gene, a key regulator of both innate and adaptive immunity, were related to the susceptibility to gastric cancer in a Chinese population." (PMID 23554619, 2010). "In summary, this study revealed that the SNP rs10759932 in the 5′-flanking region of TLR4 was associated with gastric cancer risk in Chinese population, which provides further important evidence that genetic variants in the TLR4 gene contribute to gastric cancer susceptibility." (PMID 23554619, 2010). "Consequently, the pathogenic mechanism of TLR4 in gastric cancer progression should be studied." (PMID 30636642, 2019). "Taken together, these data indicate that TLR4 is overexpressed in gastric cancer and suggest the possibility that TLR4 may be a useful biomarker and therapeutic target for gastric cancer, but the precise molecular mechanism underlying regulation of TLR4 transcription is unclear." (PMID 26675260, 2016). "Gastric cancer-derived HMGB1-enriched exosomes activate the TLR4/NF-κB pathway in neutrophils, triggering the autophagy-dependent secretion of IL-1β and OSM." (PMID 40564191, 2025). "Conversely, gastric cancer cell-derived exosomes (GC-Exs) induce N2 polarisation through the HMGB1/TLR4/nuclear factor kappa-light-chain-enhancer of activated B cells (NF-κB) pathway, promoting metastasis." (PMID 41451221, 2025). "GC-Ex activates neutrophils through the HMGB1/TLR4/NF-κB signaling pathway, thereby promoting tumor metastasis in gastric cancer." (PMID 40564191, 2025). "The new strategy can be used for other types of cancer, e.g., oral squamous cell carcinoma expressing TLR9 and gastric cancer expressing TLR4." (PMID 38390872, 2024). "For TLR4 rs7869402 polymorphism, it has been reported to reduce the susceptibility to non-small cell lung cancer (NSCLC), small cell lung cancer (SCLC), and gastric cancer, suggesting a protective role in these cancers." (PMID 39026223, 2024). "Exosomes derived from gastric cancer cells prolong the survival of TANs, induce the expression of inflammatory factors, trigger autophagy, activate TANs through the HMGB1/TLR4/NF-κB signaling pathway, and enhance gastric cancer cell migration." (PMID 39050856, 2024). "In another study, conducted on gastric cancer samples from Iranian patients, an upregulation of the TLR-4 signaling pathway was observed." (PMID 39451226, 2024). "To explore the specific mechanism by which LDN reduces postoperative complications, we conducted scientific research on gastric cancer tissue and analysed the expression levels of TLR4, IL-6 and TNF-α." (PMID 38720250, 2024). "In DCs, the expression of TLR4 was downregulated by pancreatic cancer cell-derived EVs, whereas in neutrophils, the NF-B pathway was activated by gastric cancer cell-derived EVs via TLR4." (PMID 39697631, 2024). "They showed that these polymorphisms, especially homozygous TLR-4 variants, were strongly associated with an increased risk of developing GC, further supporting the hypothesis of a key role of TLR-4 in the pathogenesis of gastric cancer." (PMID 39451226, 2024).